TTR (transthyretin)
Diseases named in the same sentence as TTR in open-access papers (continued):
Sharing a sentence is not in itself a finding about the gene and the disease.
Obesity (continued). "This study was performed only in male rats to avoid the effect of modulation of estrogen on the cardiovascular system; however, a comparison between the two sexes could provide a more comprehensive view of how obesity and mitochondrial oxidative stress could impact transthyretin levels and effects." (PMID 35897655, 2022). "Transtyretin is bound to RBP4 in plasma and an elevation in RBP4 is thought to contribute to the development of IR associated with obesity and T2DM A decrease in transthyretin could result in increased free RBP4 levels contributing to IR in obese subjects, with weight loss improving this impairment." (PMID 24949022, 2014). "Collectively, the reciprocal shift from protective proteins like TTR, APOD, and PRDX2 to pro-inflammatory mediators such as CRP and C9 highlights a coordinated reprogramming of adiposome cargo in obesity." (PMID 40981199, 2025). "Future research should seek to compare treatment pathways between patients with tumors who develop TTR-HO and those who do not; this would provide valuable insight on the medical burden due exclusively to obesity and metabolic comorbidities." (PMID 39814823, 2025). "We next tested whether chronic icv infusion of TTR into OLETF rats can produce similar reversal effects on hyperphagia and obesity as seen in exercise OLETF rats." (PMID 27053000, 2016). "Furthermore, chronic icv infusion of TTR into OLETF rats lowered DMH NPY levels and ameliorated hyperphagia and obesity." (PMID 27053000, 2016). "Chronic icv infusion of TTR in OLETF rats reversed their hyperphagia and obesity." (PMID 27512691, 2016). "However, a previous study has shown that circulating RBP4 and TTR were not affected by human obesity or T2DM, compared to lean controls." (PMID 25142320, 2014).
type 2 diabetes (21 papers, 2008 to 2024). "The objective of this study was to elucidate the relationship between RBP4, TTR, triglyceride (TG) and type 2 diabetes risk in rural Thailand." (PMID 29747616, 2018). "No such studies seem to have been published.Generally, islets in type-2 diabetic patients contained proportionally morestrongly TTR-reactive cells in accordance with the known loss of beta cells inthat disease." (PMID 18825272, 2008). "In women with osteoporosis and in older adults with type 2 diabetes mellitus (T2DM), the plasma level of TTR was specifically associated with low bone mineral density." (PMID 34359938, 2021). "Higher levels of TTR are also detected in diabetes type II and gestational diabetes, suggesting that TTR levels must be kept in balance within healthy intervals." (PMID 32197355, 2020). "Student’s t-test, Pearson’s correlation and logistic regression analysis were used to evaluate the relationships between RBP4, TTR and type 2 diabetes markers." (PMID 29747616, 2018). "Some systemic amyloidoses (e.g., light chain [AL], serum amyloid protein A [AA] and transthyretin [ATTR]) are rare, whereas other visceral amyloid-related diseases (e.g., type 2 diabetes and dialysis arthropathy) are far more common." (PMID 23750281, 2013). "In the presentstudy, we also evaluated the TTR immunoreactivity in alpha and beta cells inconjunction with type-2 diabetes." (PMID 18825272, 2008). "Moreover, expression of TTR seems to be altered in endocrine cells of the Langerhans islet in type 2 diabetes." (PMID 34199897, 2021). "Taking into account that TTR may be increased in diabetes type II, this protein might have inhibitory functions under hyperglycemic conditions, from the early stage of DR." (PMID 32197355, 2020). "Methionine oxidized TTR represented a potential biomarker for type 2 diabetes." (PMID 31504048, 2019). "It is important to note that TTR levels are increased in type 2 diabetes, while they are decreased in type 1 diabetes, suggesting that TTR levels must be kept in balance within healthy intervals, not high nor low, otherwise they may contribute to the development of pathological conditions." (PMID 34199897, 2021). "In addition, recent experimental evidence obtained by ISIS using the standard TTR ASO platform suggests that the anti-TTR therapy could play a role for the treatment of type 2 diabetes." (PMID 26437390, 2015). "It is suggested that islet expression of transthyretin may be altered in type-2 diabetes." (PMID 18825272, 2008). "Each disorder has a distinct clinical profile and is associated with the aggregation of a predominant peptide or protein, i.e. amyloid-β peptide (Aβ) in AD, transthyretin (TTR) in FAP, or amylin in type II diabetes." (PMID 27455834, 2016). "Similarly, thyroid hormone-binding protein transthyretin (Ttr) downregulated by fasting, is increased in insulin-resistant mice, and lowing thyroid hormone-binding protein levels may enhance insulin sensitivity in type 2 diabetes." (PMID 22096593, 2011). "Sincewe were not aware of any study of islet TTR in type-2 diabetes, another aim wasto study the immunoreactivity of islet alpha (glucagon) and beta (insulin)cells in diabetic and nondiabetic individuals." (PMID 18825272, 2008).
autonomic dysfunction (20 papers, 2013 to 2025). "In Portugal, it is mainly linked to transthyretin (TTR) mutation, and patients present with length-dependent sensory-motor polyneuropathy, often accompanied by autonomic dysfunction." (PMID 38449948, 2024). "As in the Taiwan cohort, our patients with the TTR Ala97Ser mutation usually presented with a late‐onset peripheral neuropathy and autonomic dysfunction." (PMID 33739616, 2021). "While 90.7% of the patients with TTR-FAP showed autonomic dysfunction mainly presenting as gastrointestinal involvement including alternative diarrhea and constipation, orthostatic hypotension and urinary dysfunction, however, were reported in only 27.8% of TTR-FAP patients." (PMID 34306035, 2021). "DNA testing, which is the most reliable test for TTR-FAP, should be performed in patients with a progressive length-dependent small fiber polyneuropathy of undetermined etiology, especially when associated with autonomic dysfunction." (PMID 23853716, 2013). "TTR-FAP usually presents itself as a progressive sensorimotor polyneuropathy, often with carpal tunnel syndrome, severe autonomic dysfunction, and cardiomyopathy." (PMID 23853716, 2013). "In patients with a known family history of TTR-FAP, the onset of symptoms and signs of peripheral neuropathy, manifestations of autonomic dysfunction, and cardiac arrhythmia call for confirmation of the involvement of these organs by appropriate investigations (see Tests and Assessments, below)." (PMID 23425518, 2013). "The proband’s onset age at third to fourth decade, sensory-motor neuropathy with autonomic dysfunction at the full development, and his father’s death 10 years after symptom’s onset were all well matched to the characteristic phenotypes of TTR-FAP, except for the amyloid-negative biopsy." (PMID 27212199, 2016).
aortic stenosis (19 papers, 2017 to 2026). Aortic valve stenosis is a aortic valve disease caused by the incomplete opening of the aortic valve. "In ATTR amyloidosis, transthyretin tetramers infiltrate the aortic valve leaflets, worsening aortic stenosis and often leading to low-flow, low-gradient aortic stenosis, particularly in males." (PMID 39330320, 2024). "Cardiac amyloidosis (CA), especially from wild-type transthyretin-related CA (wtATTR), may be prevalent in older male patients with aortic stenosis (AS) and promote increased risk of mortality." (PMID 29212513, 2017).
atrial fibrillation (19 papers, 2017 to 2026). A disorder characterized by an electrocardiographic finding of a supraventricular arrhythmia characterized by the replacement of consistent P waves by rapid oscillations or fibrillatory waves that vary in size, shape and timing and are accompanied by an irregular ventricular response. "Although higher mean TTR in warfarin therapy was associated with lower complication rates in atrial fibrillation, the strength of the association was decreased when adjusting for differences in relevant clinical characteristics of the patient cohorts." (PMID 29155884, 2017). "It should be acknowledged, however, that the median TTR found in our study was similar with the one reported in recent randomized trials on atrial fibrillation and venous thromboembolism (from 55 to 65%)." (PMID 40178736, 2025). "It is unknown whether apical sparing may contribute to the development of atrial fibrillation or—taking our data on LV amyloid load into account—potentially also indicates increased atrial TTR load." (PMID 41168134, 2025). "Clinical trials have investigated ASOs for lowering low-density lipoprotein cholesterol (LDL-C), lowering transthyretin (TTR) blood levels, reducing atrial fibrillation burden, reducing serum lipoprotein (a) levels, and preventing neovascular glaucoma." (PMID 34959335, 2021). "However, as atrial fibrillation is not a diastolic dysfunction determinant in ATTRv, atrial infiltration could also be related to age and/or different depositions from wild-type transthyretin fibrils." (PMID 34768408, 2021).
hypertrophic cardiomyopathy (19 papers, 2019 to 2026). A condition in which the myocardium is hypertrophied without an obvious cause. "Both molecular strategies in hypertrophic cardiomyopathy patients are useful for the identification of pathogenic/likely pathogenic variants in TTR/GLA genes." (PMID 40495216, 2025). "We report a rare case of hypertrophic cardiomyopathy (HCM) caused by a heterozygous variant in TTR gene." (PMID 37335747, 2023). "In case of ATTR-CA, TTR gene sequencing is recommended to confirm or exclude ATTRm, as well as other forms of hypertrophic cardiomyopathy, if indicated." (PMID 31359320, 2019).
COVID-19 (18 papers, 2021 to 2025). A disease caused by infection with severe acute respiratory syndrome coronavirus 2. "Misfolding and aggregation of TTR, causing amyloid thyroxine protein amyloidosis, has been reported associated with a higher risk of COVID-19 morbidity and mortality." (PMID 36930526, 2023). "Recently, the plasma concentration of TTR was shown to be positively associated with the outcome of COVID-19." (PMID 34359938, 2021). "Associations of TTR with severity of COVID-19 confirm that TTR contributes to a balance between fibrinolytic and coagulation systems." (PMID 34359938, 2021). "By taking the intersection of COVID-19/HCC genes and vitamin D-associated targets, we obtained seven overlapping genes (HMOX1, MB, TLR4, ALB, TTR, ACTA1 and RBP4) of vitamin D against COVID-19/HCC." (PMID 36275701, 2022). "Upon admission, a lower nutritional prognostic index and higher CRP/TTR and CRP/Albumin ratios were related to a higher probability of developing severe COVID-19." (PMID 39125329, 2024). "Next, we further analyzed the possible binding of vitamin D with the seven COVID-19/HCC targets (HMOX1, MB, TLR4, ALB, TTR, ACTA1 and RBP4) identified previously and found that vitamin D only binds to MB and RBP4." (PMID 36275701, 2022). "In all 4 assessed COVID-19 tissues, SARS-CoV-2 S transcripts were observed in 20–30% of cells per image, from which the majority corresponded to TTR+ ChP epithelial cells, except in one patient (P3) in which an equal number of not further defined stromal cells were SARS-CoV-2 S+." (PMID 37875964, 2023). "Moreover, we identified seven possible pharmacological targets of vitamin D against COVID-19/HCC, including HMOX1, MB, TLR4, ALB, TTR, ACTA1 and RBP4." (PMID 36275701, 2022). "Transthyretin levels in COVID-19 patients were searched in the literature, but no valid documents were found." (PMID 35154611, 2021). "Further, we identified seven overlapping genes of vitamin D against HCC and COVID-19 using the network pharmacology approach, and the anti-COVID-19/HCC effects of vitamin D may be modulated by these molecules or genes, including HMOX1, MB, TLR4, ALB, TTR, ACTA1 and RBP4." (PMID 36275701, 2022).
Insulin resistance (18 papers, 2011 to 2025). Increased resistance towards insulin, that is, diminished effectiveness of insulin in reducing blood glucose levels. "Nevertheless, the results of the present study suggest associations between RBP4, TTR, TG, and insulin resistance." (PMID 29747616, 2018). "The objective of the present study was to investigate whether RBP4 and TTR are associated with insulin resistance, prediabetes and triglyceride levels in rural Thais with high T2DM risk." (PMID 29747616, 2018). "In accordance with these findings, we observed an increase in TTR plasma levels in obese rats with insulin resistance, as suggested by an increase in HOMA index values." (PMID 35897655, 2022). "For example, a protein complex, which includes transthyretin (TTR), serum retinol-binding protein (RBP4), and retinol (ROH), was presented in peripheral blood and known to be associated with the development of insulin resistance." (PMID 32724825, 2020). "RBP4 and TTR levels, as well as homeostatic model assessment of insulin resistance (HOMA-IR) values, were significantly elevated among subjects with high triglyceride levels (p < 0.01, p < 0.05, p < 0.05, respectively)." (PMID 29747616, 2018). "There is evidence to suggest that RBP4 and TTR play a role in the development of insulin resistance and metabolic syndrome." (PMID 29747616, 2018). "For instance, a recent study conducted on obese mice showed that lowering RBP4 level by disrupting TTR was effective in improving insulin resistance and adipose tissue inflammation." (PMID 28713486, 2017). "TTR may have other functions with significance for marine mammal stress physiology, as it also transports RBP4, an adipokine associated with insulin resistance." (PMID 39498350, 2024). "Therefore, the confirmed low levels of Transthyretin and Dermcidin in athletes suggest a role of these proteins in adaptative response to sports and two potential new targets for treating insulin resistance." (PMID 35360242, 2022). "The present data proved that GHR not only promoted the secretion of RBP4 from the liver by activating STAT5 but also maintained circulating RBP4 homeostasis and repressed renal clearance of RBP4 by provoking activation of the HIF1α/TTR axis, thus inducing systemic insulin resistance." (PMID 34373742, 2021). "Previous study reported that the RBP4:retinol ratio and the RBP4:transthyretin ratio might be more informative than RBP4 levels alone when assessing insulin resistance during pregnancy." (PMID 31921323, 2020). "This might result from specific assay characteristics and/or intrinsic characteristics of RBP4 present in insulin resistance such as altered RBP4·TTR interactions or C-terminal RBP4 proteolysis." (PMID 29416053, 2018). "Interestingly, elevated TTR levels in insulin-resistance ob/ob mice was also reported." (PMID 30395577, 2018). "In the hypothalamus, metabolism enhancing TTR expression was upregulated, and the PTPN1 level denoting insulin resistance was downregulated, while NPY, AGRP, POMC, CART levels denoting leptin resistance showed a normalizing trend." (PMID 32943760, 2021). "A decrease in TTR may increase free RBP4 levels, promoting insulin resistance during stress responses." (PMID 39498350, 2024). "This perhaps suggests that ghrelin cell-derived RBP4 and TTR may not impact whole body insulin resistance and/or thyroid hormone transport." (PMID 23840311, 2013).
lung carcinoma (18 papers, 2013 to 2025). "Analysis by SELDI-TOF of 227 sera showed 5 peaks (m/z 11530, 11700, 13780, 13900, 14070) identifying native serum amyloid A protein and transthyretin, and some of their variants as lung cancer biomarkers." (PMID 23401773, 2013). "In lung cancer, there is mixed evidence as to whether TTR is beneficial or pathogenic." (PMID 40717228, 2025). "Some studies show that TTR suppresses lung cancer cells, arresting division, promoting apoptosis, and inhibiting growth in models of lung cancer." (PMID 40717228, 2025). "Similar cut-off, if applied on our population, where even healthy females have circulating TTR lower than the threshold value set for the lung cancer diagnosis, is likely to result in large number of false-positives." (PMID 28117336, 2017). "The transthyretin expression was significantly lower in lung cancer sera compared with sera from normal individuals, but higher compared with those obtained from benign lung disease." (PMID 23401773, 2013). "This was comparable to the TTR isoform found in sera of lung cancer patients and in CSF of patients with first-onset psychosis." (PMID 23723977, 2013). "Additionally, the serum TTR level has been reported to be a prognostic biomarker in pancreatic, and lung cancers." (PMID 38902713, 2024). "In addition, the TTR (degree = 13) is selectively highly expressed in lung cancer cells and can be secreted out of cells." (PMID 36339610, 2022). "TTR, a protein responsible for the transport of thyroxine from the bloodstream to the brain, is significantly elevated in the serum of patients with glioblastoma and lung cancer." (PMID 23723977, 2013). "It has been reported that transthyretin, a secreted protein downstream of STAT3, could promote oncogenic gene activation, enhance cytokine function in the tumor microenvironment as well as increase the production of reactive oxygen species to facilitate the progression of lung cancer." (PMID 36338720, 2022). "The results of immunofluorescent studies revealed no changes in the expression of glycolytic enzymes in mouse lung cancer cell line (KLN205), human skin fibroblasts, nor human immortalized epithelial cells (ME16C) after stimulation with TTR." (PMID 29290976, 2017).
hepatoma (17 papers, 2013 to 2023). "Differential levels of TTR in serum have been linked to several cancers, including breast, ovarian and hepatocellular carcinomas." (PMID 24935269, 2014). "Anyway, studies on human and rat hepatoma cell lines highlighted that also, in this case, TTR tetramers were endocytosed by a receptor-mediated process which resulted in being saturable (Kd between ~4 and ~10 nM vs. ~5 μM TTR plasma concentration)." (PMID 36009453, 2022). "For example, serum transthyretin is found to be a significant independent factor for overall survival (OS) in the intrahepatic cholangiocarcinoma and hepatocellular carcinoma." (PMID 31275452, 2019). "A set of 400 TTR ASO compounds was originally screened in the human hepatoma cell line HepG2 and also evaluated in a TTR Ile84Ser transgenic mouse model." (PMID 26437390, 2015). "In hepatoma cell lines and in mouse primary hepatocytes, WT TTR internalization was described to be a receptor-mediated process." (PMID 25395306, 2015). "However, in agreement with our study, the study did demonstrate that HDL was able to reduce TTR uptake in rat hepatoma cells." (PMID 31316837, 2019). "Our previous studies of SerpinA1 downregulation showed significantly increased TTR serum levels in HM30 mice, as well as in hepatoma cells." (PMID 34502397, 2021). "Moreover, the same authors also showed that TTR increased Aβ internalization by SAHep cells (human hepatoma cells) and by primary hepatocytes derived from TTR+/+ mice when compared to TTR−/− animals." (PMID 33212973, 2020). "We next searched by immunoblotting for SMT in the secretion media of a human hepatoma cell line that does not produce/secrete endogenous TTR after infection with lentiviral vector stocks that lead to the production and secretion of WT and V30M TTR." (PMID 23387326, 2013).